ENSG00000252337
Gene: Small nucleolar RNA gene on chromosome 5 (106,546,665 to 106,546,803, forward strand). Ensembl gene ENSG00000252337.
Homologues: Paralogues in human: SNORA31B (75% identical), SNORA31 (61% identical).